TLR9 (toll like receptor 9)
Diseases named in the same sentence as TLR9 in open-access papers (continued):
Sharing a sentence is not in itself a finding about the gene and the disease.
pulmonary tuberculosis (11 papers, 2011 to 2024). A bacterial infection that affects the lungs and is caused by Mycobacterium tuberculosis. "In a Vietnamese cohort study in TLR9 polymorphism, rs352142G/T was associated with meningeal TB while rs352143A/G was associated with pulmonary TB." (PMID 30167433, 2018). "We carried out a case–control association community based study, genotyping 12 polymorphisms of TLR2, TLR4, TLR6 and TLR9 genes in 90 patients with confirmed pulmonary TB and 90 unrelated exposed but asymptomatic household contacts." (PMID 24053111, 2013). "The present study revealed the synergic effect of TI,II/CC genotypes of TLR4 Thr399Ile and TLR9 T-1486C polymorphisms with the increasing risk of pulmonary TB." (PMID 23766695, 2013). "Variants in TLR4, Asp299Gly and Thr399Ile, and the TLR9-1486C/T were investigated for their association with susceptibility or resistance to pulmonary tuberculosis." (PMID 23766695, 2013). "Therefore, to determine whether TLR4 and TLR9 are associated with susceptibility to pulmonary TB in the current study, two common TLR4 polymorphisms, Asp299Gly and Thr399Ile, and one well-known TLR9 gene polymorphism, T-1486C, were examined." (PMID 23766695, 2013). "Therefore, we examined whether polymorphisms in TLR2, TLR4, TLR6 and TLR9 are associated with the susceptibility to pulmonary TB in Mexican individuals from a rural area with high incidence of TB." (PMID 24053111, 2013). "Polymorphic loci rs5743708 (TLR2) influence the risk of developing LTBI and subsequent pulmonary tuberculosis in the Chinese population, and variations in rs7873784 (TLR4) and rs5743836 (TLR9) influence the risk of developing LTBI and pulmonary tuberculosis." (PMID 39339847, 2024). "The aim of the present study was to investigate the potential association between pulmonary TB, a TB infection of the lungs, and three SNPs in TLR4 and TLR9 genes in southeastern Iranian population, Zahedan." (PMID 23766695, 2013). "The objectives of this study were to determine whether TLR8 and TLR9 SNPs were associated with the development of latent TB infection (LTBI) and the subsequent pulmonary TB (PTB) in a Chinese Han population." (PMID 30424735, 2018). "The second limitation is the lack of functional assays to determine the effect of TLR9 variation in the susceptibility to pulmonary TB." (PMID 24053111, 2013). "The frequencies of T-1486C TLR9 genotypes and alleles were not significantly different between pulmonary TB patients and the controls." (PMID 23766695, 2013). "The analysis revealed the association of TLR2 “CC” genotype (rs3804100C/T) and TLR9 “TC” genotype (rs5743836) with LTBI susceptibility and TLR2 “GA” genotype (rs5743708A/G), TLR4 “GG” genotype (rs7873784C/G) and TLR8 “CC” genotype (rs3764879C/G) with susceptibility to pulmonary TB." (PMID 30167433, 2018).
bacterial meningitis (10 papers, 2012 to 2024). Inflammation of the membranes surrounding the brain and spinal cord due to a bacterial infection. "A meta-analysis revealed that the TLR9 polymorphism rs352140 is associated with a decreased risk of bacterial meningitis." (PMID 38891900, 2024). "In Angolan children, the single nucleotide polymorphism TLR4 rs4986790 increases the susceptibility to bacterial meningitis caused by Haemophilus influenzae, the risk of ataxia, and neurological sequelae, while TLR9 rs187084 decreases the risk." (PMID 38891900, 2024). "Some studies have suggested that the Toll-like receptor 9 polymorphism (TLR9 rs352140) is closely related to the risk of bacterial meningitis (BM), but this is subject to controversy." (PMID 33143777, 2020). "In this study, only one SNP of TLR4 and TLR9 was tested, and the possible effects of the other SNPs in the two genes on the susceptibility to and outcome of bacterial meningitis should also be kept in mind." (PMID 32967147, 2020). "Our finding suggested that genetic variations in TLR2 and TLR9 are associated with severity and prognosis of bacterial meningitis in Chinese children." (PMID 28202935, 2017). "Stimulation of TLR9 signalling “trains” the innate immunity against Gram-positive and Gram-negative pathogens and provides cross-protection to common pathogens causing bacterial meningitis." (PMID 33531028, 2021). "Next, we determined the genotype frequencies of TLR9 -1237 and TLR9 +2848 polymorphisms and compared these between thirteen clinical variables associated with prognostic factors predicting adverse outcome of bacterial meningitis in children." (PMID 22577991, 2012). "For example, in mice, the induction of edema by ammonia injection requires expression of toll-like receptor 9 (TLR9), which is also required for the inflammatory response to bacterial meningitis." (PMID 33391257, 2020). "Our finding supports a role of genetic variation of TLR2 and TLR9 in severity and prognosis of Chinese Han children to bacterial meningitis." (PMID 28202935, 2017). "Among TLRs, TLR2, TLR4, TLR9 are involved in the pathogenesis of bacterial meningitis." (PMID 33808027, 2021). "We investigated whether bacterial meningitis (BM) in children was associated with gene polymorphisms in TLR2 (rs3804099), TLR3 (rs3775291 and rs3775290) and TLR9 (rs352139 and rs352140)." (PMID 28202935, 2017). "Eleven SNPs in seven genes (TLR2, TLR4, TLR9, NOD1, NOD2, CASP1, and TRAIL) were genotyped in 393 survivors of childhood bacterial meningitis (BM) (327 MM patients and 66 PM patients)." (PMID 22662111, 2012).
Granuloma (10 papers, 2012 to 2024). A compact, organized collection of mature mononuclear phagocytes, which may be but is not necessarily accompanied by accessory features such as necrosis. "The role of TLR9 was also investigated in LCL due to L. (V. ) braziliensis showing a strong association with granuloma in the dermis of cutaneous lesions of patients, principally in macrophage cells." (PMID 29543867, 2018). "Thus, the lower expression of CCL20 during mycobacterial challenge in either TLR9-deficient mice or anti-dll4–treated lungs might contribute to the observed decreased DC numbers during pulmonary granuloma formation." (PMID 23386849, 2013). "Little has been observed in terms of the role of TLR9 in ACL, with exception of a single publication demonstrating that the expression of that receptor was associated with granuloma in the LCL form caused by L. (V. ) braziliensis." (PMID 29543867, 2018). "Our data on TLRs in granulomas in patients with cutaneous leishmaniasis are in accordance with the literature, where TLR9 and TLR2 have been reported." (PMID 25397678, 2014). "Our results show a contribution of TLR9 to the elimination of P. acnes from the host and reveal the existence of a delayed, TLR9-independent mechanism of granuloma formation in response to P. acnes treatment." (PMID 22745710, 2012). "The exact reason for this difference is unclear but the authors speculated that higher TLR9 in granulomas could possibly have been a mechanism of parasite control and the avoidance of more generalized and widespread dermatitis." (PMID 26465878, 2015). "However, another study shows that FIZZ1 expression level is enhanced in exacerbated Sm egg-induced granuloma formation in TLR-9 KO mouse." (PMID 24516640, 2014). "More recently, our group showed the first analysis of cell-mediated Th17-related pulmonary mycobacterial Ag-elicited granuloma formation in TLR9−/− mice and defined a role for TLR9 in the induction of both Notch ligand Dll4 and Th17 expression using both in vivo and in vitro approaches." (PMID 23386849, 2013). "TLR9 expression has been demonstrated in granulomas from L. braziliensis patients but the evolution of this response was not studied and may relate to TLR9 regulation on macrophages after granuloma formation." (PMID 26678994, 2016). "Interestingly, the alternative TLR9-independent activation mechanism leads to the same immune phenotype as the TLR9-dependent one, i.e. intrahepatic granuloma formation, splenomegaly, hypersensitivity to TLR ligands and endogenous mediators and enhanced resistance to infection." (PMID 22745710, 2012). "Adverse effects, including fever, chronic inflammation, and granuloma, were reported using a combination of TLR1/2, TLR9, and TLR8 agonists in swine." (PMID 39355141, 2024). "One of the studies, reported adverse effects, including fever, chronic inflammation, and granuloma in the use of TLR1/2, TLR9, and TLR8 agonists combination administered intramuscularly in swine." (PMID 39355141, 2024). "The TLR2-/-, TLR9-/- and TLR2/9-/- mice exposed to SR all demonstrated granuloma formation suggesting that additional PRRs must be involved in granuloma formation in HP." (PMID 24023674, 2013). "As expected for animals with impaired TLR9 signaling, we observed no splenomegaly, LPS hypersensitivity, or intrahepatic granulomas (not shown) in the 3d mice on day 7 after priming." (PMID 22745710, 2012). "To determine whether TLRs 2 and 9 also control neutrophil recruitment throughout 3 weeks of repeated exposures (at which time granulomas develop) we exposed WT, TLR2-/-, TLR9-/-, and TLR2/9-/- mice to SR 3 times / week for 3 weeks and performed BAL one day after the last exposure." (PMID 24023674, 2013).
head and neck squamous cell carcinoma (10 papers, 2019 to 2025). A squamous cell carcinoma that arises from any of the following anatomic sites: lip and oral cavity, nasal cavity, paranasal sinuses, pharynx, larynx, and salivary glands. "In a phase 2 trial in head and neck squamous cell carcinoma, responses to the TLR9 agonist SD-101 occurred in both PD-L1 high and low tumors, suggesting benefits for patients who do not respond to ICIs due to low PD-L1 levels." (PMID 41086813, 2025). "Clinical responses to TLR9 for head and neck squamous cell carcinoma occurred in both PD-L1 high and low tumors, suggesting a benefit for patients who do not respond to ICIs due to low PD-L1 levels." (PMID 41086813, 2025). "TLR-9, TLR-5, TLR-4, TLR-3, TLR-2 and TLR-1 are linked to some clinical parameters of patients afflicted with head and neck squamous cell carcinoma (HNSCC)." (PMID 36224753, 2022). "TLR9 agonists have been studied with ICBs in multiple tumor types, including melanoma, lymphoma, head and neck squamous cell carcinoma (HNSCC), and NSCLC." (PMID 35292881, 2022). "Combining anti-PD-1 with CMP-001 (a TLR-9 agonist) to treat head and neck squamous cell carcinoma (HNSCC) had a better effect and prolonged the survival time of mouse, compared with anti-PD-1 alone." (PMID 33469538, 2020). "In head and neck squamous cell carcinoma (HNSCC), a combination of intratumoral injections of TLR7 and TLR9 agonists with PD-1 blockade suppresses tumor growth and promotes systemic adaptive immunity." (PMID 38732254, 2024). "TLR9 agonist candidates SD-101 and CMP-001 were well tolerated in early phase clinical trials and demonstrated clinical activity in combination with anti-PD-1 treatment in melanoma and head and neck squamous cell carcinoma (HNSCC)." (PMID 33572196, 2021). "Notably, in clinical investigations of head and neck squamous cell carcinoma (HNSCC), multiple studies have evaluated TLR8/9 agonists—including the TLR8 agonist motolimod and TLR9 agonists SD-101, IMO-2055, and EMD1201081—in combination with cetuximab or PD-1 inhibitors." (PMID 41488647, 2025).
myocardial infarction (10 papers, 2013 to 2025). Gross necrosis of the myocardium, as a result of interruption of the blood supply to the area, as in coronary thrombosis. "Studies had shown that acute myocardial infarction can cause aseptic inflammation, aggravate tissue damage, and lead to increased levels of mtDNA, which activates the NF-κB pathway through TLR9 and triggers an innate immune response, leading to myocardial cell damage." (PMID 34795807, 2021). "mtDNA released in acute myocardial infarction activates TLR9 and aggravates ischemia reperfusion injury through the TLR9-p38 MAPK pathway, thus exacerbating myocardial injury." (PMID 34795807, 2021). "Our previous study demonstrated that TLR9 can affect myocardial apoptosis in HMGB1‐mediated post‐myocardial infarction tissue repair." (PMID 33140921, 2020). "In an acute myocardial infarction model, mtDNA activates NF‐κB by activating TLR9, which thereby leads to mitochondrial dysfunction and cardiomyocyte death." (PMID 33140921, 2020). "We have previously reported that TLR9 prevents cardiac rupture after myocardial infarction by promoting proliferation and differentiation of cardiac fibroblasts." (PMID 31160091, 2019). "In this study, we observed highly increased gene expression levels of Tlr1, Tlr2, Tlr6, Tlr7, Tlr8, Tlr9 as well as Irf7 in the scar tissue after myocardial infarction, indicating their relevance to a proper cardiac wound healing." (PMID 29538462, 2018). "After myocardial infarction, gene expression levels of the intracellular localized Tlr7, Tlr8, and Tlr9 were significantly increased when compared to their healthy controls." (PMID 29538462, 2018). "TLR9 can also prevent cardiac rupture after myocardial infarction." (PMID 33138323, 2020). "In a model of myocardial infarction, free DNA from NETs can enhance the proliferation of Mer tyrosine kinase/Major Histocompatibility Complex II macrophages (Mertk-MHC-IIlo-int) through the Toll-like receptor 9 pathway." (PMID 40109341, 2025). "This study demonstrates that TLR9 is essential for the repair of infarcted myocardium and interaction of HMGB1 and TLR9 is involved in the survival of myocardial cells, wound healing, and angiogenesis after myocardial infarction." (PMID 31209243, 2019). "Interestingly, post myocardial infarction TLR and IRF gene expression was almost exclusively increased in the infarct zone after myocardial ischemia (Tlr2, Tlr3, Tlr6, Tlr7, Tlr9, Irf3, Irf7)." (PMID 29538462, 2018).
Splenomegaly (10 papers, 2012 to 2025). Abnormal increased size of the spleen. "TLR9 agonist causes dramatic splenomegaly in mice (p<0.001) as compared with untreated and control oligo-treated mice, indicating an expansion of splenocytes with TLR9 agonist." (PMID 22666458, 2012). "Previously we observed that Tlr9-/- MRL.Faslpr mice had significantly worse splenomegaly compared to Tlr9+/+ MRL.Faslpr." (PMID 28278279, 2017). "2B, in both wt and TLR9−/− mice the development of splenomegaly, another characteristic P. acnes immune effect, correlated timely with the development of P. acnes-induced LPS hypersensitivity." (PMID 22745710, 2012). "Indeed, mice that received constant TLR9 stimulation developed splenomegaly indicating a systemic immune response, although there was no change in overall bodyweight across all treatment groups." (PMID 38201300, 2024). "We analyzed the spleens of CpG ODN and buffer-treated mice and observed that CpG ODN-related splenomegaly occurred in both immunocompetent and neutropenic wild-type animals but not in TLR9-deficient mice." (PMID 33531028, 2021). "Analysis of Pld4thss/thssTlr9−/− mice revealed that the splenomegaly characteristic of Pld4thss/thss mice was completely normalized in the absence of TLR9, as measured by spleen weight and counts of nucleated cells." (PMID 37555846, 2023). "However, 10-mo-old DNase II−/−Ifnar1−/− mice have been reported to develop splenomegaly and produce antinuclear antibodies in a STING- or AIM2-independent manner; instead, Unc93b, which regulates the localization of several TLRs (e.g., TLR3, TLR7, and TLR9) to the endosome, is required." (PMID 34901991, 2022).
allergic rhinitis (9 papers, 2007 to 2017). Inflammation of the nasal mucous membranes caused by an IgE-mediated response to external allergens. "For instance, subcutaneous administration of alum vaccine of ragweed-TLR9 agonist was clinically effective in the treatment of allergic rhinitis." (PMID 26380316, 2015). "The present study was designed to examine the expression of TLR9 in the nasal mucosa and in leukocytes derived from different cellular compartments during symptomatic allergic rhinitis." (PMID 17328813, 2007). "Also, subcutaneous administration of a ragweed-TLR9 agonist vaccine was clinically effective in allergic rhinitis treatment." (PMID 28220116, 2017). "Therefore, our finding of a lower expression of TLR4 and TLR9 in the nasal mucosal of allergic rhinitis patients may be related to the Th2-type allergic inflammation and to the increased susceptibility to upper respiratory infections usually observed in rhinitis patients." (PMID 22577387, 2012). "Confocal analysis of the inflammatory nasal mucosa in allergic rhinitis revealed a marked downregulation of both TLR4 and TLR9." (PMID 22577387, 2012). "Hence, the present study was designed to investigate the expression of TLR9 in human nasal mucosa and in leukocytes derived from bone marrow, peripheral blood and nasal lavage fluid, with focus on compartmental differences and possible changes during symptomatic allergic rhinitis." (PMID 17328813, 2007). "The onset of symptomatic allergic rhinitis did not affect the TLR9 expression in any of the compartments investigated." (PMID 17328813, 2007).
Crohn disease (9 papers, 2007 to 2022). A gastrointestinal disorder characterized by chronic inflammation involving all layers of the intestinal wall, noncaseating granulomas affecting the intestinal wall and regional lymph nodes, and transmural fibrosis. "The gene encoding for TLR9 is mapped on chromosome 3p21.3 in the vicinity of a shared susceptibility locus for Crohn's disease and ulcerative colitis." (PMID 26090491, 2015). "TLR9(T1237C) expression also has increased prevalence in Crohn’s disease, particularly among those with NOD2 mutations and IL23R variants." (PMID 26361369, 2015). "Genetic evidence supports a role of PRR in IBD, since polymorphisms in NOD2 and to a lower extent in TLR9 genes have been linked with Crohn's disease." (PMID 17375199, 2007). "The interactions between TLR9 polymorphisms and allelic variants in NOD2 and IL23R differentially modulate susceptibility to Crohn's disease." (PMID 26090491, 2015). "Furthermore, in an experimental study using a mice model of Crohn's disease-like ileitis, it was found that TLR9 plays an important role in hepatic involvement in IBD." (PMID 28659988, 2017).